C12orf56 (chromosome 12 open reading frame 56)
Tractability: PROTAC: ubiquitination databases record sites on it.
Gene: Protein-coding gene on chromosome 12 (64,264,762 to 64,390,758, reverse strand). Ensembl gene ENSG00000185306.
Genetic constraint (gnomAD): Loss-of-function variants: 49 observed, 45.95 expected, observed/expected ratio (o/e) 1.07, 90% interval 0.85 to 1.35. The upper end of that interval is the gene's LOEUF score, 1.35, which puts it in group 5 of 6, group 1 being the genes least tolerant of losing a copy. Missense variants: 623 observed, 614.83 expected, observed/expected ratio (o/e) 1.01, 90% interval 0.95 to 1.08. Synonymous variants: 235 observed, 240.51 expected, observed/expected ratio (o/e) 0.98, 90% interval 0.88 to 1.09.
Homologues: Orthologues: chimpanzee C12H12orf56 (99% identical), macaque C11H12orf56 (95% identical), pig C12orf56 (83% identical), rabbit C12orf56 (83% identical), dog C12orf56 (80% identical), mouse D930020B18Rik (75% identical), guinea pig C12orf56 (71% identical), rat C7h12orf56 (60% identical), zebrafish si:ch211-258f14.2 (31% identical).
Diseases named in the same sentence as C12orf56 in open-access papers:
C12orf56 is named in the same sentence as 2 diseases in open-access papers, as found by Europe PMC text mining. Sharing a sentence is not in itself a finding about the gene and the disease. The quoted sentences say what the papers report.
lung adenocarcinoma (1 paper, 2023). A carcinoma that arises from the lung and is characterized by the presence of malignant glandular epithelial cells. "Among them, low expression of C12orf56, DLX5, DSC3, FEZF1, GSTA1, H2BC9, IGSF11 and high expression of EREG, CEACAM6, SLC34A2 in lung adenocarcinoma were found to predict poor prognosis for patients." (PMID 37035196, 2023).
tumor (1 paper, 2025). "C12orf56 was expressed at higher levels in normal samples, whereas EREG and INHBB were expressed at higher levels in tumor samples." (PMID 39883700, 2025).